HLA-E (major histocompatibility complex, class I, E)
Diseases named in the same sentence as HLA-E in open-access papers (continued):
Sharing a sentence is not in itself a finding about the gene and the disease.
influenza (5 papers, 2014 to 2025). An acute viral infection of the respiratory tract, occurring in isolated cases, in epidemics, or in pandemics; it is caused by serologically different strains of viruses (influenzaviruses) designated A, B, and C, has a 3-day incubation period, and usually lasts for 3 to 10 days. "Indeed, this observation is in line with two recent reports describing the ability of Qa-1, the murine orthologue of HLA-E in humans, and HLA-E to bind influenza-derived epitopes." (PMID 39030218, 2024). "Specifically, influenza samples maintained higher levels of type I IFN response–associated antiviral ISGs (e.g., IFITM1, IFITM2, IFITM3, OAS2, OAS3, OASL) and antigen presentation genes (e.g., HLA-DRB5, HLA-C, B2M, HLA-B, HLA-E)." (PMID 34618691, 2021). "Therefore, this is a common phenomenon that HLA-E*01 and HLA-A*02 molecules could present the same epitopes, such as influenza M159-167, M158-166, and Epstein–Barr virus BZLF139-147 due to conserved deep pockets." (PMID 38257752, 2023).
lung carcinoma (5 papers, 2011 to 2025). "Conversely, our study demonstrated a significant lower expression of HLA‐E in lung cancer and its association with reduced survival." (PMID 39623605, 2024). "Therefore, we initially examined the expression of HLA‐E in lung cancer tissues and explored its association with survival outcomes." (PMID 39623605, 2024). "Our study unveils a novel immunosuppressive mechanism in lung cancer with pleural metastasis, driven by the interplay between cancer cell senescence and HLA-E expression." (PMID 40959273, 2025). "Further investigations are warranted to explore the therapeutic potential of IRF5 and HLA‐E in lung cancer treatment." (PMID 39623605, 2024). "Although our study provides significant insights into the role of IRF5 and HLA‐E in lung cancer treatment, there are still certain limitations." (PMID 39623605, 2024). "It was found that antibody CAB024589 was used for immunohistochemical analysis of both cancer and normal tissues, revealing a significantly elevated expression of HLA‐E protein in lung cancer tissues compared to adjacent normal tissues." (PMID 39623605, 2024). "In conclusion, our study reveals the potential role of IRF5 derived from M1‐like macrophage exosomes in lung cancer treatment through the upregulation of HLA‐E expression, thus providing a novel theoretical foundation for future immunotherapy strategies." (PMID 39623605, 2024). "Coculturing M1‐exos or si‐IRF5 M1‐exos with lung cancer cells from both Vector and OE‐HLA‐E groups demonstrated that overexpression of HLA‐E led to decreased metabolic activity and viability of A549 and SPC‐A1 cells, irrespective of coculture conditions." (PMID 39623605, 2024). "Collectively, these findings suggest that IRF5 regulates lung cancer cell growth through its interaction with HLA‐E, wherein overexpression of HLA‐E can counteract the tumor‐promoting effects induced by si‐IRF5 M1‐exos." (PMID 39623605, 2024). "Next, we further investigated the potential involvement of HLA‐E in the growth of lung cancer cells mediated by IRF5." (PMID 39623605, 2024). "Additionally, the UALCAN database indicated a correlation between HLA‐E expression levels and individual stages of lung cancer." (PMID 39623605, 2024). "Although HLA‐E is a potential target for tumor immunotherapy, its role in lung cancer remains unclear." (PMID 39623605, 2024). "Furthermore, we validated the role of HLA‐E in regulating lung cancer growth mediated by IRF5 M1‐exos." (PMID 39623605, 2024). "Nevertheless, the expression and role of HLA‐E in lung cancer remain elusive." (PMID 39623605, 2024). "Western blot analysis revealed an increase in HLA‐E protein expression in the M1‐exos group compared to the PBS group, and lung cancer cells cocultured with IRF5 M1‐exos exhibited higher levels of HLA‐E expression." (PMID 39623605, 2024). "To study HLA-E-mediated inhibition of NK cell cytotoxicity, we induced HLA-E expression in four different solid tumor cell lines: the human breast adenocarcinomas MDA-MB-231 and SK-BR-3, the lung carcinoma A549, and the colorectal adenocarcinoma HT-29." (PMID 37675109, 2023). "Given that HLA‐E is a downstream target gene of IRF5, we speculated that HLA‐E may be involved in the regulation of lung cancer cell growth by IRF5." (PMID 39623605, 2024). "Despite limited research on the correlation between IRF5 and HLA‐E in human lung cancer, it is hypothesized that IRF5 could play a crucial role in regulating HLA‐E expression." (PMID 39623605, 2024). "We investigated the impact of IRF5 M1‐exos on lung cancer cell proliferation and tumor growth and, for the first time, identified that alterations in IRF5 expression result in significant upregulation of HLA‐E expression and promoter activity in lung cancer cell lines." (PMID 39623605, 2024). "Notably, the mechanism by which IRF5 exerts its antitumor function through HLA‐E regulation in lung cancer has not been fully elucidated." (PMID 39623605, 2024).
lung carcinoma (continued). "In contrast to what was expected, in humans the presence of CTLs was only beneficial in patients with lung carcinoma if HLA-E was not expressed by the tumor, indicating that HLA-E restricted CTLs may not directly contribute to tumor elimination in these patients." (PMID 27699181, 2016).
metastatic tumors (5 papers, 2011 to 2021). "Noticeably, HLA-E/β2m overexpression profile by tumor cells was concordant between primary and paired metastatic tumors in the majority of cases (31/39, 79.5%) but discordant in 8 (20.5%) cases." (PMID 34211852, 2021). "HLA-E/β2m was preferentially overexpressed in metastatic tumors (12/39, 30.8%) compared with primary tumors (8/39 cases, 20.5%)." (PMID 34211852, 2021). "In the xenograft experiment in mice, tumors with high HLA-E expression grew rapidly and expressed high levels of IL-10 and TGF-β in plasma and tumor tissue and were associated with metastatic disease in bone marrow." (PMID 27322426, 2016). "Cells from the bone marrow of one patient with high HLA-E expression in the tumor tissue and confirmed metastatic disease in the bone marrow were cultured to produce a cell line named NB-Ehigh in this study." (PMID 27322426, 2016). "On the other hand, patients with stage IV disease exhibited lower levels of sHLA-E, which is in accordance with the faint spontaneous expression of HLA-E by metastatic tumor sections that we previously reported by immunohistochemistry." (PMID 21712991, 2011). "In principle, we suggest that anticancer NK immunotherapy requires determination of the degree of expression of HLA-E on patients' primary or metastatic tumors, with higher expression indicating those most likely to respond to monospecific anti-HLA-E mAb enhancement of cytotoxicity." (PMID 31009335, 2019). "Furthermore, our study, the first to explore and compare the expression profile of this new immune checkpoint in paired primary and metastatic tumors of mCRC patients, demonstrates that HLA-E/β2m is preferentially expressed by tumor cells in metastases compared with primary tumors." (PMID 34211852, 2021).
renal cell carcinoma (5 papers, 2012 to 2023). "This indicates that overexpression of HLA-E decreases the immunogenicity of cells with renal cell carcinoma and may therefore play a role in promoting immune surveillance evasion." (PMID 33767709, 2021).
type 1 diabetes (5 papers, 2011 to 2019). "There is limited evidence to suggest that certain HLA-E genotypes (HLA-E107R/G) are associated with age at onset of type 1 diabetes." (PMID 31820163, 2019). "The locus in HLA-E has been strongly associated with type 1 diabetes." (PMID 21569557, 2011). "Firstly, it was shown that HLA-E gene polymorphism was associated with the development of several human diseases such as ankylosing spondylitis, Kawasaki disease, rheumatoid arthritis, type 1 diabetes mellitus, pemphigus vulgaris, psoriatic arthritis, and hepatitis C virus infection." (PMID 31569411, 2019). "The data suggest that the functional impairment of HLA-E-restricted CD8+ Treg cells in type 1 diabetes can be corrected through in vitro re-stimulation." (PMID 31569411, 2019). "Interestingly, T-cells reactive with self Hsp60sp presented by HLA-E have also been identified, both in healthy donors and in patients with type 1 diabetes." (PMID 27699181, 2016). "Furthermore, there is a defect in CD8+ T-cell recognition of HLA-E/Hsp60sp in patients with type I diabetes." (PMID 27699181, 2016). "However, studies utilising the unique type 1 diabetes pancreas resection material from recently diagnosed patients enrolled in the Norwegian DiViD study demonstrated that HLA-E RNA expression was elevated in inflamed islets when compared with islets from control pancreata." (PMID 31820163, 2019). "This review focuses on the current understanding of the non-classical HLA-I subtypes: HLA-E, HLA-F and HLA-G, within and outside the field of type 1 diabetes, and considers the possible impacts of these molecules on disease etiology." (PMID 31820163, 2019). "HLA-E expression was particularly high in the non-infiltrated islet core of the type 1 diabetes donors when compared to the peri-islet area that contained infiltrating immune cells, which suggests that the islet cells rather than the immune cells have the highest expression [43••]." (PMID 31820163, 2019).
B cell lymphomas (4 papers, 2020 to 2021). "However, the impact of genetic variants in NKG2C and HLA-E on clinical outcomes of aggressive B-cell non-Hodgkin lymphoma patients (B-NHL) has not been clarified." (PMID 33218185, 2020). "Selinexor is currently being assessed in a clinical trial in combination with anti-CD20 antibodies for patients with advanced B cell non-Hodgkin lymphoma (NCT03147885) and HLA-E downregulation by selinexor may therefore contribute to ADCC in this setting." (PMID 34926302, 2021).
cervical adenocarcinoma (4 papers, 2012 to 2025). An adenocarcinoma arising from the cervical epithelium. "Additionally, we showed that HLA-E was overexpressed more frequently in cervical adenocarcinoma than squamous cell carcinoma." (PMID 25795131, 2015).
chronic GvHD (4 papers, 2019 to 2023). "Interestingly, symptoms of chronic GvHD were observed among recipients with HLA-E mismatched donors more frequently (3/7 cases, 42.86%) than among matched pairs (11/53 cases, 20.75%), however, this difference did not rich statistical significance (p=0.339)." (PMID 37901227, 2023).
endometriosis (4 papers, 2019 to 2024). The growth of functional endometrial tissue in anatomic sites outside the uterine body. "It is also possible that endometriosis is associated with the upregulated expression of the inhibitory NKG2A receptor that is bound by HLA-E molecules." (PMID 31540116, 2019). "CD94/NKG2A is upregulated in the peritoneal fluid of endometriosis patients and decreases NK cell cytotoxicity upon binding of its ligand HLA-E." (PMID 35628346, 2022). "This is evidenced, for instance, by the finding of significantly higher levels of HLA-E mRNA (which binds to the C-type lectin protein HLAI-specific inhibitory NK receptor CD94/NKG2A) in the peritoneal fluid of endometriosis subjects compared with controls." (PMID 36613776, 2022). "Moreover, it has been previously proposed that the KLRC1/HLA-E axis is involved in a hypothetical escape mechanism in which endometriosis ectopic expression of HLA-E inhibits NK cytotoxic activity." (PMID 39684780, 2024). "The increased expression of inhibitory NKG2A receptor may constitute one of the NK cell checkpoints and may contribute to the immunopathogenesis of endometriosis, therefore, further investigations on the HLA-E expression in endometriotic tissues are strongly encouraged." (PMID 31540116, 2019). "Patients with endometriosis have a higher expression of the CD94/NKG2A receptor on NK cells, and upon binding of its ligand HLA-E, NK cell function is inhibited." (PMID 35628346, 2022). "Endometriosis pathogenesis seems to be marked by the overexpression of NK inhibitor receptors (KIRS), namely, CD158a+, KIR2DL1, CD94/NKG2A, PD-1, NKB1, and EB6, and inhibiting ligands such as PD-L1, HLA-E, HLA-G, and HLA-I." (PMID 36613776, 2022). "As per their results, endometriosis pathogenesis is marked by the overexpression of NK inhibitor receptors (KIRS), namely, CD158a+, KIR2DL1, CD94/NKG2A, PD-1, NKB1, and EB6, and inhibiting ligands such as PD-L1, HLA-E, HLA-G, and HLA-I in ectopic endometrial lesions." (PMID 36613776, 2022).
gynecological cancers (4 papers, 2019 to 2024). "Increased ERAP2 expression is associated with increased HLA-E in gynecological cancers, and cytotoxic lymphocyte infiltration is lowered with HLA-E expression." (PMID 36834865, 2023). "Furthermore, in gynecologic cancers, high HLA-E expression in patients abrogated the survival benefit of high levels of cytotoxic tumor-infiltrating lymphocytes, suggesting that tumor HLA-E expression is a relevant factor when considering ICB or adoptive cell therapies for patients." (PMID 35082797, 2021).
hepatocellular carcinoma (4 papers, 2019 to 2025). A malignant tumor that arises from hepatocytes. "in their mRNA expression analysis in hepatocellular carcinoma patients showed that higher HLA-E mRNA levels were associated with worse DFS." (PMID 40066089, 2025). "HLA-E was found to be expressed on the surface of human hepatoma cells, resulting in negative regulation of NK cell activity through CD94/NKG2A interaction." (PMID 37371767, 2023). "Consistent with these functional studies, the expression of NKG2A and HLA-E in hepatocellular carcinoma (HCC) tissues correlated with poor prognosis of HCC patients." (PMID 31552017, 2019). "Besides, the expression of NKG2A and HLA-E in hepatocellular carcinoma (HCC) tissues corresponded with poor prognosis in HCC patients, confirming these functional investigations." (PMID 36109471, 2023).
pancreatic ductal adenocarcinoma (4 papers, 2022 to 2025). An infiltrating adenocarcinoma that arises from the epithelial cells of the pancreas. "Other groups identified HLA-E in circulating tumor cells derived from pancreatic ductal adenocarcinoma." (PMID 38902472, 2024). "Specifically, in cases such as pancreatic ductal adenocarcinoma, Monalizumab (IPH2201), a human IgG4 blocking monoclonal antibody targeting inhibitory NKG2A on NK cells and a subset of CD8+ T cells, disrupts the interaction between inhibitory NKG2A and HLA-E." (PMID 38272918, 2024).
acute leukemia (3 papers, 2020 to 2023). A clonal (malignant) hematopoietic disorder with an acute onset, affecting the bone marrow and the peripheral blood. "HLA-E mismatch between the donor and recipient patients with acute leukemia was found to be associated with a better five-year overall survival and lower graft vs. host disease incidence in the recipient patients." (PMID 36671682, 2023).
breast tumors (3 papers, 2013 to 2024). "Based on the tolerogenic functions of breast tumors, we investigated possible associations between the expression of HLA class Ia, class Ib (HLA-G and HLA-E), and class II (HLA-DQ and HLA-DR) in breast tissue." (PMID 24363939, 2013).
esophageal squamous cell carcinoma (3 papers, 2023 to 2025). Esophageal squamous cell carcinoma (ESCC) is a type of esophageal carcinoma (EC) that can affect any part of the esophagus, but is usually located in the upper or middle third. "The prognostic impact of human leukocyte antigen-E (HLA-E) expression and the proportion of natural killer (NK) cells in esophageal squamous cell carcinoma (ESCC) was investigated." (PMID 39845968, 2024).
infertile (3 papers, 2016 to 2025). "It seems that by genotyping of HLA-E polymorphism, we can predict the risk of RSA in infertile women." (PMID 27525333, 2016). "Therefore, a comprehensive stratified meta-analysis considering sex, ethnicity, and infertility subtype is crucial to clarify HLA-E’s role in reproductive outcomes." (PMID 41321564, 2025). "Similarly, HLA-E molecules, the ligand of the inhibitory NKG2A receptor, are down-modulated during HHV-6A infection and slightly reduced in endometrial epithelial cells from HHV-6A positive infertile women, thus promoting an activatory profile." (PMID 29326672, 2017).
myeloid leukemia (3 papers, 2024 to 2026). A clonal proliferation of myeloid cells and their precursors in the bone marrow, peripheral blood, and spleen. "BAP1 knockdown across multiple myeloid leukemia cell lines selectively decreased HLA-E and IFN-γ-R1 expression in ASXL1-mutant backgrounds." (PMID 42295372, 2026).
preeclampsia (3 papers, 2014 to 2023). Preeclampsia is a hypertensive disorder of pregnancy that is characterized by new-onset hypertension with proteinuria presenting after 20 weeks of gestation, and depending on mild or severe forms may initially present with severe headache, visual disturbances, and hyperreflexia. "If HLA-E expression is hypothesized to be important in the context of pregnancy, an association of preeclampsia with HLA-E polymorphisms seems relevant to investigate." (PMID 25566263, 2014). "In severe preeclampsia, NK cell adhesion to the endothelium is significantly higher than in normal pregnancy, implying an interaction with an overexpressed HLA-E in the endothelial cell membrane." (PMID 37206444, 2023). "The functions of HLA-E and HLA-F in pregnancy and preeclampsia are less well-described and warrant further investigation." (PMID 35571013, 2022). "A possible role of terminal α2-3 sialic acid in the HLA-E α1-domain could be relevant to explain this activation profile in peripheral NK cells mediated by NKG2 receptor activation in severe stages of preeclampsia." (PMID 37206444, 2023).
renal carcinoma (3 papers, 2016 to 2024). A carcinoma arising from the epithelium of the renal parenchyma or the renal pelvis. "However, contradictory evidence indicates that patients who have cervical or renal carcinoma and high HLA-E expression have good prognoses." (PMID 27322426, 2016).
rheumatoid arthritis (3 papers, 2016 to 2023). A chronic, systemic autoimmune disorder characterized by inflammation in the synovial membranes and articular surfaces. "In rheumatoid arthritis (RA), limited information is available, although HLA-E polymorphisms may be associated with disease susceptibility and treatment responsiveness." (PMID 27699181, 2016).
sarcoma (3 papers, 2011 to 2024). A usually aggressive malignant neoplasm of the soft tissue or bone. "Cell‐cell communication analysis showed that SD3 enriched sarcoma cell subtype sarco_2 had low expression of HLA‐DRA, HLA‐E, HLA‐F and HLA‐A, and high expression of ICAM1 and TGFB1." (PMID 39658531, 2024). "After performing validation in both TCGA dataset and GEO dataset GSE17679, we extracted a group of immune-related genes, including NR1H3, VAMP5, GIMAP2, GBP2, HLA-E and CRIP1 that were most significant to predict good outcomes in sarcoma patients." (PMID 33316779, 2020).
schizophrenia (3 papers, 2012 to 2021). A major psychotic disorder characterized by abnormalities in the perception or expression of reality. "From the pathway enrichment analysis, subnetwork 26 was enriched with proteins involved in an antigen processing and presentation pathway that consisted of three PCOSrps (HLA-A, HLA-C, and HLA-E) shared between PCOS and schizophrenia." (PMID 31216618, 2019). "All three sets of module genes include well-studied candidate genes for schizophrenia (e.g., DTNBP1), glutamate receptors (e.g., GRIN1), several genes located in the MHC region (e.g., HIST1H1A, HIST1H1C, HIST1H2AB, HIST1H2BB, HLA-E), and genes from the 14-3-3 protein family (e.g., YWHAQ, YWHAZ)." (PMID 23134571, 2012).